CD4 (CD4 molecule)
Diseases named in the same sentence as CD4 in open-access papers (continued):
Sharing a sentence is not in itself a finding about the gene and the disease.
infection (continued). "As the infection continued, wild-type mice presented IFN-γ-producing (CD4+CD44+ and CD8+CD44+) T cells both in the spleen and heart while B2R−/− mice showed negligible frequencies of such activated T cells." (PMID 18052532, 2007). "In this manuscript we identify a subset of human CD4+ T cells, which we termed TEMRA cells, that express CCR5 but still remain resistant to infection." (PMID 17465678, 2007). "When considered as a proportion, it can be seen that CD4+CD25+ cells outgrow CD4+CD25– cells from day 7 onwards and remain in significant excess over uninfected controls throughout infection." (PMID 17563918, 2007). "We found that production of IFN-γ by Ag-experienced CD4+ and CD8+ T cells from B2R−/− spleen and heart declined sharply as the infection continued (28 d p.i.)." (PMID 18052532, 2007). "Different phenotypes were observed among the virus isolates and in many cases CD4-independent infection was at a very low level and was only rescued after cocultivation of infected NP-2/CCR5 cells with hPBMC, defined as CD4-independent-LOW phenotype." (PMID 17645788, 2007). "Eight days following infection, CD8+ and CD4+ T cell responses were measured by peptide-induced IFN-γ production and cytolytic killing of peptide-pulsed target cells." (PMID 17570849, 2007). "Incident HSV-2 infection – that is seroconversion or acquisition of HSV-2 after infection HIV-1 – was observed in our cohort, and analyzed separately for its effect on viral load and CD4+ T cell count." (PMID 17957262, 2007). "Infection of mice with LCMVClone13 induces anergy in CD4 and CD8 T cells, whereas infection with LCMVARM leads to robust immunity." (PMID 17570849, 2007). "As the infection advanced (14→28 d), wild-type mice developed high frequencies of IFN-γ-producing CD4+ and CD8+ effector T cells, both in the spleen and heart." (PMID 18052532, 2007). "Our findings that TEMRA cells are expanded in a portion of HIV-infected individuals and are highly resistant to R5-tropic infection prompted us to examine relationships between high TEMRA cells and CD4 numbers." (PMID 17465678, 2007). "HIV-1 entered CD4+ T cells almost exclusively by CD4 and CCR5 receptor-mediated direct fusion, without requiring passage from Langerhans cells, and overt productive infection ensued." (PMID 17306567, 2007). "Severe thymus atrophy with a reduction of CD4 and CD8 double positive T cells was also observed in the lethal infection." (PMID 17326843, 2007). "The dynamics of this binding at 37°C resembled binding of an HIV fusion mutant to CD4-positive cells, indicating that most of HIV-GFP arrested infection of HFA at the stage of virus-cell fusion." (PMID 17498309, 2007). "Many CD4+ cells, such as T cells and monocytes are infected by HIV-1, these cells circulate in the blood and can cross the BBB and propagate the infection within the CNS." (PMID 16712719, 2006). "The nature of the interactions of CD4, CCR5, DC-SIGN and HSPGs with HIV-1 Env during infection have implications for intervention strategies." (PMID 16817962, 2006). "In these proof-of-concept studies we show that RAG-hu mice are permissive to infection with both R5 and X4 tropic HIV-1, displaying prolonged viremia and CD4 T cell depletion characteristic of HIV infection and disease in the human." (PMID 17078891, 2006). "It is noteworthy in this respect that heterozygous CCR5 mutations in two of the five EUs studied here (B184 and W336) were associated with low CCR5 surface expression on their primary CD4 T cells and with resistance of these cells to HIV-1 R5 infection." (PMID 17092330, 2006). "The present study demonstrates the presence of a broad repertoire of TLRs in T cells, a differential expression in CD4+ and CD8+ cells, along with infection-dependent alterations in TLR expression." (PMID 16504163, 2006).
infection (continued). "We previously reported that by employing a gp120-independent infection mechanism, HIV-1 virus infected several CD4(-) cell lines, including oral cell lines Tu139 and Tu177, prostate cell lines LNCaP and DU145, and the fibroblast cell line, HT-1080." (PMID 16368003, 2005). "During infection, HIV-1 uses CD4 as its primary receptor and a member of the chemokine receptor family like CXCR4 or CCR5 as a coreceptor." (PMID 16371160, 2005). "We found a large, clinically significant correlation between the number of T-helper cells (CD4) and global self-assessed quality of life (QOL1) (r = 0.57, p = 0.021), when controlled for age, gender, and years of infection." (PMID 15167940, 2004). "The resulting complex blocks virus binding to CD4 and CXCR4/CCR5 and inhibits infection by primary virus clades A to G and group O." (PMID 15485580, 2004). "Both CD4+ and CD8+ cells were poorly infected, although there was indication of an increased infection of low-CD8 T lymphocytes in comparison with high-CD8 cells." (PMID 15555076, 2004). "An infection with Cryptosporidium felis in an HIV-positive man from Italy was successfully treated with paromomycin, despite the patient’s having a CD4+ cell count of 31/mL." (PMID 11749756, 2002). "Two out of five participants showed a decrease in rca-RNA, but this did not correlate with the infection levels in resting CD4+ T cells." (PMID 41424846, 2026). "In contrast, TNFR1, which is structurally similar to TNFR2 and shares the same ligand, failed to inhibit the infection of CD4+ T cells by HIV-1 pseudoviruses." (PMID 42088414, 2026). "Cell-mediated immune response-like kinetics of CD4+ and CD8+ T lymphocytes showed a sharp decline during the early stage and an increase of CD8+ T lymphocytes during later stages of infection." (PMID 41884535, 2026). "This approach confirmed that while CD4+ and CD8+T cells formed their own distinct clusters, a significant and separatepopulation of lymphocytes expressed the γδ T cell receptor,forming a unique island that clearly expanded upon infection." (PMID 41365681, 2026). "Soon after HIV-1 exposure, these cells migrate to draining lymph nodes and transfer it to CD4+ T cells through virological synapses in the absence of a productive infection." (PMID 40143294, 2025). "Increased CD4+CD25+Foxp3+ Tregs have also been documented in the peritoneal cavity of mice intraperitoneally infected with E. multilocularis, and their depletion improved infection control." (PMID 40725240, 2025). "The median CD4+ count for patients without infection was 344.5 cells/μL (IQR: 135–478), whereas for patients with infection, it was 358 cells/μL (IQR: 99–551) (p = 0.019)." (PMID 40005357, 2025). "Interestingly, SARS-CoV-2 Delta breakthrough infection did induce significantly higher anti-S and anti-N CD4 and CD8 T cells responses in BAL cells in the acute phase of the breakthrough infection." (PMID 41390777, 2025). "In contrast, ECTV infection of BMDCs silenced for CtsB, L, or S did not affect cytokine production, maturation, or CD4+ T cell stimulation, indicating that modulation of DC function by ECTV occurs largely independently of cathepsins." (PMID 41369389, 2025). "In fact, only two clusters increased in size in the third compared with first infection—a small subset of double negative (DN) T cells and a cluster of T-betlo Eomesneg effector memory CD4+ T cells." (PMID 40214640, 2025). "Strikingly, our data also argue against a scenario in which non-infected CD4+ T cells enhance macrophage infection by viral replication and re-transmission." (PMID 40130873, 2025). "SARS-CoV-2-specific CD4 T and CD8 T cells are detectable in the lymphoid tissues of the URT, LRT, and elsewhere in the body after an infection, and these include memory CD4 T and CD8 T cells present long after SARS-CoV-2 infections, including asymptomatic infections." (PMID 41471153, 2025).
infection (continued). "Our findings reveal unexpected dynamics in the CD4+ and CD8+ T-cell compartments following booster vaccination and breakthrough infection and provide essential insights into the complex interplay between vaccination and breakthrough infection in shaping T and NK-cell immunity against SARS-CoV-2." (PMID 40977733, 2025). "Importantly, natural SIV hosts have evolved to reduce the expression of the viral receptor CD4 or the viral coreceptor CCR5 and protect their target cells from infection." (PMID 39842407, 2025). "Consistently, we observed that patients with positive IgA, IgG and IgM responses on day 1 of infection displayed high frequencies of HLA-DR+CD38+ CD4+ T cells compared to HIV-1 negative individuals, but not significant." (PMID 40607402, 2025). "Immunological parameters, including lymphocyte subsets (CD3+, CD4+, CD8+, CD19+, and NK), the IRI (CD4+/CD8+), and the absolute number of leucocytes and lymphocytes, correlated with severity of infection and were summarised by mean, standard deviation, and median in an exploratory data analysis." (PMID 40005306, 2025). "The Treg cells were significantly upregulated during the early phases of the mpox disease, especially in the HIV+ subjects (T0 = 30.3% of CD4+) compared with the HIV− subjects (T0 = 11.0%, event count difference p < 0.01), with a trend of normalization with the resolution of infection." (PMID 40005722, 2025). "We have now shown that among the MP CD4 T cells generated in the absence of infection, there is a population of MP Tfh cells." (PMID 39568245, 2025). "Notably, ECs exhibited significantly lower BTLA expression in activated CD4+ T cells (49 and 133 days post-infection) and TIGIT expression in activated CD8+ T cells (49, 84, and 133 days post-infection)." (PMID 40637373, 2025). "The exact contribution of these cytotoxic CD4+ T cells to infection resolution is not fully elucidated." (PMID 41012193, 2025). "Upon infection of mice with the non-lethal strain Plasmodium yoelii (Py), 4-1BB was preferentially upregulated on splenic CD4 T cells." (PMID 40215168, 2025). "Conversely, inadequate CD4+ T-cell gain directly impacts the infection’s prognosis and indicates immunological nonresponse." (PMID 40260259, 2025). "This led to significantly lower levels of infection of untreated CTV-labeled bystander CD4+ T cells (~0.5% p24+ cells); and iii) treated CTV-labeled bystander CD4+ T cells were protected from infection in the presence of untreated, productively infected CD4+ T cells (2–2.5% HIV+ cells)." (PMID 40166014, 2025). "While we observed higher frequencies of DENV-specific CD4+ T cells in the preinapparent group compared with the presymptomatic group following 2+ DENV infections, this difference was not statistically significant (P = 0.3011)." (PMID 39989460, 2025). "Recent studies have challenged the notion of the restriction of the HIV reservoir to CD4+ T cells, showing productive infection of non-lymphoid cells, including monocytes and several classes of macrophages." (PMID 41143136, 2025). "From early in infection, PD-1 expression levels are higher in SD versus non-SD in CD4+/CD8+ T and NK-cells, and these remain significantly higher at TP2 for CD8+ T-cells, suggesting prolonged antigenic stimulation of these cells in SD." (PMID 40595657, 2025). "Notably, among all infections, FoxP3+ T cells (Tregs and CD25-FoxP3+ cells) showed a higher proportion (0.5%–1%) than effector CD4+ T cells (Th1 and Th17; <0.5%) relative to the overall CD4+ αβ T cell population (3%–5%) at 14 dpi." (PMID 40459260, 2025). "The highest rates of infection were found among patients with CD4 + counts < 200 cells/μL, no history of ART, animal contact, and use of well water." (PMID 41372782, 2025).
infection (continued). "To determine the contribution of CD4+ T cells in modulating the formation and activation of IgG+ memory B cell (IgG+ MBC) (CD3-CD20+CD27+sIgG+) populations during a primary DENV2 infection, we measured expression levels of surface IgG in total MBCs via flow cytometry." (PMID 41295476, 2025). "These CD4+ (T helper) cells support or promote the antiviral effect of CD8+ cells and can offer long-term immune protection to lessen the intensity of COVID-19 symptoms and react quickly to infection." (PMID 40868058, 2025). "No changes in naïve CD4+ T cells or central memory CD4+ T cells were observed during either infection." (PMID 40512037, 2025). "By contrast, IFN-γ secretion by CD4+ T cells was shown to be critical for protective activity as early as 4 weeks post-infection when transferred into recipient mice lacking both αβ and γδ T cells (Trcb–/–Tcrδ–/–)." (PMID 40489538, 2025). "Our data indicate that RSV can increase its pathogenesis through infection of nonclassic monocytes, leading to a CD4+ T-cell imbalance." (PMID 39656009, 2025). "Stem-like CD4+ T cells retain transcriptional and epigenetic features that closely resemble those of naïve and TCM cells, which are critical for protective immunity against infections." (PMID 40634636, 2025). "Given that CD4-GPI and CXCR4-318 seemed likely candidates to be incorporated into HIV-1 particles, and that they efficiently mediated cell–cell fusion reactions, we tested their propensity for targeting the infection of Env-expressing cells." (PMID 40284914, 2025). "To further elucidate the methylation patterns in distinct T cell subsets, we examined methylation levels associated with characteristic cytokines and transcription factors in naïve CD4+ T cells, as well as Th1, Th17, Th9, and Th22 cells, which play a pivotal role in human TPE infection immunity." (PMID 40170749, 2025). "Surprisingly, anti–VLA-4/LFA-1 failed to prevent CD4+ T cell migration into the brain at day 14 after infection, despite persistent changes in bacterial burdens and innate immune cell infiltrates, revealing a sustained footprint with early T cell blockade." (PMID 39989461, 2025). "The ChAdOx1 vaccine induces a Th1-biased response characterized by IFN-γ and TNF-α secretion by CD4+ T cells, predominant IgG1/IgG3 production, and CD8+ T cells with cytotoxic potential, and has demonstrated efficacy against symptomatic infection by the ancestral SARS-CoV-2 strain." (PMID 41346576, 2025). "Moreover, epi-DCs support productive infection of HIV and are significantly more efficient at mediating both first- and second-phase transfer to CD4 T cells." (PMID 40929143, 2025). "The percentage of CD4+ T cells among the TCRγδ− cells did not significantly differ from that among the control group after infection, whereas the percentage of CD8+ T cells among the TCRγδ− cells significantly decreased at 4 and 6 dpi." (PMID 41168865, 2025). "Indeed, when individuals with up to 7 days of infection were included in the analysis, we observed an increase in the frequency of T cells with a regulatory and exhausted phenotype (PD‐1+ Foxp3+ CD25+ CD4+T cells)." (PMID 40388115, 2025). "Although B, CD4+, and CD8+ T cells are detected within the CNS tissue, their role is contradictory: they may help combat infection or contribute to neuropathology." (PMID 41472211, 2025). "In contrast to the decrease in CD4+ T cells, CD8+ T cells, and CD19+ B cells, there was a significant increase in the number of CD163+ macrophages and CD56+ NK cells in the peripheral lymphoid organs upon the infection." (PMID 40143222, 2025). "However, Trim29IEC-KO adult mice had significantly higher frequencies of intraepithelial IFN-γ-expressing CD4+ T cells and Granzyme B-expressing CD4+ T cells in small intestines than Trim29fl/fl mice after EMCV infection for 3 days." (PMID 39396665, 2025).
infection (continued). "However, S- as well as N-specific CD4 and CD8 T cells were strongly induced by the Delta breakthrough infection and peaked at week 18, 2 weeks after infection." (PMID 41390777, 2025). "Additionally, WCCs had higher levels of CD3+CD4+ T lymphocytes and lower levels of CD3+CD8α+ T lymphocytes, both before and after infection, compared to RWFCs." (PMID 40941329, 2025). "Prior to infection, we verified that CCL19-treated CD4 + T cells exhibited minimal expression of CD69 and CD25, confirming a resting phenotype, whereas cells treated with phytohaemagglutinin (PHA) and interleukin-2 (IL-2) for 24 hours showed robust upregulation of both markers." (PMID 40372991, 2025). "CD4+ T cells with high coexpression of the PD-1 and ICOS activation markers increased in frequency from approximately 0.1% at baseline to a peak of approximately 1%–2% between weeks 8 and 21 after infection." (PMID 40956619, 2025). "Finally, cell-mediated immunity, particularly memory CD4+ and CD8+ T cell responses, plays a more prominent role in limiting disease progression than in preventing infection." (PMID 41251472, 2025). "Following primary infection, which occurs exclusively through cell-to-cell transmission, viral persistence is primarily maintained by clonal expansion of infected CD4+ T cells rather than by de novo infection." (PMID 40431676, 2025). "However, the donor OT1 POSHfl/fl CD4-Cre CD8 T cells were significantly reduced by days 15 and 28 post-infection." (PMID 40672960, 2025). "CD4+ and CD8+ T lymphocytes are central in controlling and clearing infections in the FRT, whereas γδ T cells, which are resident in the intraepithelial layer of the FRT mucosa, provide a defensive barrier and exert a potent cytolytic effect against pathogenic microorganisms." (PMID 41295582, 2025). "The CD99 signaling network demonstrated increased activity in NK cell and Platelets, with significant connection with T cell:CD4+ effector memory, T cell:CD4+ central memory and Pre‐B cell CD34‐, emphasizing their capacity to contribute to inflammatory mediators' processes after infection." (PMID 40910395, 2025). "However, following infection with the lentivirus, both the expression level and MFI of NKG2D on CD4+ T cells in the NKG2D-CAR T and IL15C-NKG2D-CAR T groups increased." (PMID 40625735, 2025). "Finally, 100 mg/kg BW baicalin upregulated the proportions of CD3+, CD3+CD4+, and CD3+CD8+ T cells compared with the infection group (p < 0.001)." (PMID 40305201, 2025). "We focused our analysis on CD69-, CD38-, CD25-, and HLA-DR-expressing CD4 T cells, along with CD69- and CD38-expressing CD8 T cells, whose frequency increased consistently across all donors upon infection with at least one strain (compared to the uninfected control)." (PMID 40162896, 2025). "Raphin1 treatment did not improve kidney function in nephritic wild-type mice in which CD4+CD69+ TRM cells were not induced by infection, indicating that CD4+CD69+ TRM cells were required for the therapeutic effect." (PMID 40050432, 2025). "Unlike infection-driven responses, autoimmune CD4+ T cells retain TCF1 expression during antigen priming, likely due to the absence of inflammatory signals associated with infections." (PMID 40634636, 2025). "In the infection context, a direct CD154 signal to macrophages could occur in the context of antigen‐specific interactions with CD4+ T cells, as all macrophage types analysed express MHCII." (PMID 41388224, 2025). "Furthermore, the progeny of the T-bet reporter-sorted CD4+ T cells showed high expression of the inhibitory receptors PD-1 and LAG3 already 7 days post infection with LCMV Cl13." (PMID 41488650, 2025). "CD4 helper T cells are essential for the effective CD8 T-cell responses, and a direct effector role of the HCMV-specific CD4 T cells in the control of the infection has also been suggested." (PMID 41376632, 2025).